ANO1 (anoctamin 1)
Diseases named in the same sentence as ANO1 in open-access papers (continued):
Sharing a sentence is not in itself a finding about the gene and the disease.
tumor (continued). "Paradoxically, tumor samples with ANO1 amplification had potentiating effects of DNA methylation, with significant hypermethylation at positively correlated CpG’s and significant hypomethylation at a negatively correlated CpG." (PMID 29123240, 2017). "Using HNSCC tumor samples from TCGA, we correlated DNA methylation at individual CpG’s within these regions with ANO1 expression." (PMID 29123240, 2017). "While the canonical Myc target genes we examined were slightly elevated in KPH2 tumours (or decreased in the case of Cdkn1a), Ano1 expression was significantly increased, suggesting other input(s) are likely influencing its transcription." (PMID 26837714, 2016). "Duvvuri and colleagues found the mitogen-activated protein kinase (MAPK) activation during ANO1-mediated tumor progression." (PMID 26811235, 2016). "KPH2 cells maintained slightly higher levels of ANO1 compared with KP in vitro, although this phenotype is more striking in tumours as they were cultured under normoxic conditions." (PMID 26837714, 2016). "Many investigations have highlighted signaling pathways of ANO1-mediated tumor progression, which requires multiple cellular events including cell proliferation, migration/invasion, tumor growth, and metastasis in vivo." (PMID 26811235, 2016). "KPH2 tumours also exhibited elevated ANO1 protein levels compared with KP tumours, although the available antibody exhibited relatively weak immunoreactivity with both KP and KPH2 tumour lysates." (PMID 26837714, 2016). "Ano1 gene amplification in tumors showed a significant correlation with poor survival rate in cancer patients, positive correlation with tumor grade, the increase in cell migration, and tumor growth or metastasis." (PMID 26811235, 2016). "Although ANO1 is considered as a potential tumor biomarker, reports on its roles in tumor progression are inconsistent." (PMID 27732935, 2016). "We found that ANO1 knockdown significantly inhibited cell proliferation and induced cell apoptosis in either tumor cell lines or normal HaCaT cell line." (PMID 27732935, 2016). "Linear regression also confirmed the significant correlation (r2=0.3246, p<0.0001) between ANO1 expression and tumor size, and the significant correlation (r2=0.0379, p=0.008) between ANO1 expression and mitotic count." (PMID 27153560, 2016). "Strikingly, we found important differences on the impact of ANO1 in patient survival depending on the anatomic site of the tumours." (PMID 26498851, 2015). "We detected ANO1 expression in 78 (22%) tumours, whilst ANO1 gene amplification occurred at a higher frequency (58%)." (PMID 26498851, 2015). "ANO1 gene amplification was detected in 35 (58%) tumour samples with relative copy numbers ranging from two- to 19-fold (median, 6.1 fold)." (PMID 26498851, 2015). "As compared with the control scrambled shRNA, the average tumor weight of ANO1 shRNA1 and shRNA2 groups was about 38.7% and 70.1%, respectively." (PMID 26305547, 2015). "Collectively, this study provides original evidence demonstrating the distinctive impact of ANO1 expression on HNSCC prognosis depending on the tumour site." (PMID 26498851, 2015). "Inhibition of ANO1 also suppressed tumor growth in nude mice implanted with stable transfected GLC82 cells." (PMID 26305547, 2015). "Genetic inhibition of ANO1 expression leads to suppression of proliferation, metastasis and invasiveness in vitro and xenograft tumor growth in vivo." (PMID 26305547, 2015). "All ANO1-positive tumours harboured ANO1 gene amplification; however, only one-third of cases with gene amplification were concomitantly accompanied by ANO1 overexpression." (PMID 26498851, 2015). "In summary, our findings demonstrate that ANO1 gene amplification occurs frequently in both premalignant lesions and invasive tumours, whereas concomitant ANO1 expression was detected at a much lower frequency." (PMID 26498851, 2015).
tumor (continued). "Further immunohistochemical staining of ANO1 in xenograft tumor confirmed that the reduction of ANO1 protein expression levels was consistent with the tumor volume in the groups treated by ANO1 shRNAs with different potency and in the control group." (PMID 26305547, 2015). "ANO1 has been suggested to drive 11q13 amplification by providing growth or metastatic advantage to tumours." (PMID 24316695, 2014). "Kaplan–Meier survival analysis showed that patients with high-level tumor expression of ANO1 had decreased overall survival." (PMID 24639373, 2014). "ANO1 inhibits ferroptosis by activating the PI3K-Akt signaling pathway, and recruits cancer-associated fibroblasts by regulating the TGF-β signaling pathway, which affects CD8 + T cell-mediated anti-tumor immunity and leads to resistance to immunotherapy." (PMID 40478912, 2025). "In this review, we elucidate the critical role of ANO1 in non-neoplastic diseases." (PMID 40356890, 2025). "Knockdown of ANO1 in the GIST xenograft model dramatically reduced tumour development." (PMID 40396170, 2025). "Aberrant overexpression of ANO1 contributed to tumor-induced immunosuppression." (PMID 40396170, 2025). "ANO1 promotes tumour growth through activation of EGFR, PI3K/AKT, and MAPK signalling pathways." (PMID 40806720, 2025). "Further investigations revealed that ANO1 amplification and overexpression are significantly correlated with tumor grade and poor prognosis, promoting tumor proliferation through the epidermal growth factor receptor (EGFR) and calmodulin-dependent protein kinase II (CAMKII) signaling pathways." (PMID 40356890, 2025). "ANO1 is essential for tumour maintenance and is considered a potential driver of HCC." (PMID 40396170, 2025). "Therefore, ANO1 can serve as a biomarker for tumor recurrence monitoring and the assessment of poor prognosis in GIST." (PMID 40356890, 2025). "Recent studies suggest that ANO1 contributes to tumor cell drug resistance." (PMID 40356890, 2025). "Furthermore, ANO1 is widely expressed across various malignancies, orchestrating multiple signaling pathways and contributing significantly to tumor initiation and progression." (PMID 40356890, 2025). "Based on these results, we hypothesized that Ano1 expression has a stronger impact on tumor cell sensitivity to radiation and CDDP, an assumption we tested in HNSCC cell line models." (PMID 39789065, 2025). "The amplification of the ANO1 gene found on chromosome 11q13 is related to several types of cancers, including those of the breast, stomach, and colon, which contribute to the abnormal cellular behaviors typical of tumor formation." (PMID 40707942, 2025). "ANO1 may induce an immunosuppressive tumor microenvironment in PC in a paracrine manner, suggesting that ANO1 may be a novel therapeutic target." (PMID 38352864, 2024). "ANO1 not only inhibits tumor apoptosis but also promotes tumor immune escape." (PMID 38352864, 2024). "Furthermore, ANO1 has been shown to stimulate the expression of TGF-β, facilitate the aggregation of tumor-associated fibroblasts, suppress the immunoreactivity of CD8+T cells, and decrease the secretion of TNF-α, granzyme B, and IFN-γ." (PMID 38853203, 2024). "This suggests that ANO1 levels can be regulated in cancer cells by cytokines, which may be the molecular mechanism by which ANO1 is involved in inflammation and tumor immunity." (PMID 38352864, 2024). "ANO1 may induce an immunosuppressive tumor microenvironment in PC cells in a paracrine manner; therefore, ANO1 may be a new therapeutic target in PC." (PMID 38352864, 2024). "Mechanistically, we found ANO1 exerted its malignant functions in promoting tumor growth/metastasis and mediating immunotherapeutic resistance through inhibiting cancer ferroptosis, an iron‐regulated cell death triggered by the accumulation of toxic lipid peroxides." (PMID 37341301, 2023).
tumor (continued). "Since ANO1 knockdown could revoke the immune‐suppressive tumor microenvironment, we evaluated the impact of inhibiting ANO1 on the effectiveness of anti‐PD‐1 antibody in MC38‐ or CT26‐engrafted C57BL‐6J/BALB‐C mice models." (PMID 37341301, 2023). "Furthermore, tumor growth was significantly reduced by intratumoral injection of ANO1 shRNA in an orthotopic xenograft mice model using PC-3 cells." (PMID 36674697, 2023). "Finally, the latest inhibitors of ANO1 are summarized, which provides the research direction for the tumor-promoting mechanism of ANO1." (PMID 35734591, 2022). "At the same time, ANO1 also resists tumor apoptosis and promotes tumor immune escape." (PMID 35734591, 2022). "Several studies had suggested an impact of ANO1 on tumor cell proliferation." (PMID 33628598, 2021). "HNSCC patients with higher ANO1 expression have fewer immune cells in the tumor microenvironment, which may be explained by the involvement of cytokine signaling-related genes, which were positively regulated with this TMEM." (PMID 34638224, 2021). "TMEM expression was also dependent on tumor invasion to space surrounding a nerve for ANO1, TMEM116, and TMEM97 (p = 0.002, p < 0.0001, p = 0.008) and on angiolymphatic invasion for TMEM48, RTP3, TMEM173, and TMEM116 (p < 0.0001, p = 0.0267, p = 0.001, p = 0.0053, respectively)." (PMID 34638224, 2021). "Although further research is needed in the future, these results suggest that downregulation of ANO1 by small-molecule inhibitors may be more harmful to tumor cells than normal cells." (PMID 32899792, 2020). "ANO1 plays a critical role in tumor growth and maintenance of these cancers." (PMID 32899792, 2020). "ANO1 protein stained positive in 19.8% (39/197) tumor tissues and 1% (2/197) normal tissues." (PMID 31793228, 2020). "ANO1 knockdown significantly reduced cell proliferation in both tumor cell lines and HaCaT cells." (PMID 32899792, 2020). "In addition, overexpression of ANO1 promotes tumor growth by activating EGFR-mediated AKT/SRC/ERK1/2 signaling or Ras-Raf-MEK-ERK1/2 signaling pathway." (PMID 32899792, 2020). "ANO1 protein was strongly stained on the cell membrane in tumor tissues." (PMID 31793228, 2020). "Complex tumor microenvironments and interaction of cytokines secreted by cancer cells and TILs may contribute to amplification of the ANO1 gene; however, these mechanisms require further research." (PMID 31266974, 2019). "Moreover, a combined analysis with ANO1 mRNA and conventional tumor markers had the highest sensitivity in diagnosing GISTs." (PMID 31266974, 2019). "In addition, ROC curve analysis showed that ANO1 mRNA in the blood had the highest specificity when compared with conventional tumor markers." (PMID 31266974, 2019). "To examine whether knockdown of ANO1 altered apoptotic signaling, we determined gene expression in the tumor xenografts." (PMID 29899325, 2018). "CLCA2 and ANO1 may be used already today as markers for circulating cancer cells to monitor efficacy of the therapy directed against the primary tumor or to estimate the systemic cancer cell burden." (PMID 27618016, 2016). "It remains unclear whether ANO1-mediated tumor progression or cell proliferation is merely due to the increased mRNA level of ANO1 or due to the augmented channel activity." (PMID 26811235, 2016). "Thus, one possible explanation for our findings is that Myc, whose level is elevated in KPH2 tumours, binds to the Ano1 promoter and increases Ano1 expression." (PMID 26837714, 2016). "For UPS tumours, loss of HIF-2α increases ANO1, promoting CaMKII and mTORC1 activity." (PMID 26837714, 2016). "The tumor-suppressing function of miR-132 may in part be realized through targeting of the downstream gene ANO1." (PMID 26868958, 2016). "However, Ano1 (encoding TMEM16A, Anoctamin-1 and DOG1) transcripts were significantly increased in KPH2 tumours relative to controls." (PMID 26837714, 2016).
tumor (continued). "Thus, it is remarkable that the functional channel activity of ANO1 is required for cell viability, promotion of tumor growth, and cell proliferation." (PMID 26811235, 2016). "Furthermore, the tumor growth in nude mice implanted with GLC82 cells was significantly suppressed by ANO1 silencing." (PMID 26305547, 2015). "It remains largely unclear how Ano1 overexpression contributes to tumor malignancy." (PMID 25961581, 2015). "Even though the role of ANO1 expression and gene amplification in tumour progression and metastatic dissemination has been investigated in different cancers, including HNSCC, its potential contribution to malignant transformation has not yet been explored in clinical samples." (PMID 26498851, 2015). "However, remarkably ANO1 expression differentially influenced patient survival depending on the tumour site." (PMID 26498851, 2015). "The invasion potential of tumor cells was dramatically suppressed by ANO1 knockdown." (PMID 26305547, 2015). "A remarkable reduction of tumor weight in ANO1 shRNA groups was observed." (PMID 26305547, 2015). "Some investigators thought that ANO1 was a tumor marker while others an oncogene 8,15." (PMID 24639373, 2014). "Although one research showed that ANO1 was overexpressed in PC, the prognostic value and specific role of ANO1 in PC progression remain unclear, and its association with the tumor microenvironment (TME) has not been explored." (PMID 38352864, 2024). "However, whether ANO1 is also involved in other secondary metastases of tumours needs further study." (PMID 38685684, 2024). "The expression of ANO1 in cancer cells, the expression of fibroblast activation protein (FAP) and alpha smooth muscle actin in cancer-associated fibroblasts (CAFs), and the numbers of CD8- and FOXP3-positive tumor-infiltrating lymphocytes (TILs) were evaluated using immunohistochemistry." (PMID 38352864, 2024). "That has become another previously unknown mechanism by which ANO1 may influence tumor progression." (PMID 34638224, 2021). "However, reports on its roles in tumor progression obtained from cancer cell lines are inconsistent, suggesting that the role of ANO1 in tumorigenesis is likely dependent on either its expression level or cell-type expressing ANO1." (PMID 27732935, 2016). "Thus, an ANO1-ERM interaction might provide a clue to the role of ANO1 in EGF-driven tumor cell migration and invasion." (PMID 26811235, 2016). "Thus, ANO1 gene amplification occurred very early during tumourigenesis, thereby being detected in patients with mild dysplasias and at a high frequency along the different stages of tumour progression." (PMID 26498851, 2015). "Thus, increased ANO1 expression may promote tumour growth, whereas decreasing ANO1 expression favours transition from an epithelial to a mesenchymal phenotype and the development of metastasis." (PMID 26498851, 2015). "Therefore, ANO1 emerges as a pleiotropic effector that seems to influence tumour proliferation and metastasis in an opposing way, which likely involves regulation through changes in phosphorylation and direct protein-protein interactions such as TMEM16A S970 and Radixin13." (PMID 26498851, 2015). "On this basis, Anoctamin-1 gene (ANO1, also termed TMEM16A, ORAOV2, DOG1, TAOS2 and FLJ10261), encoding a calcium-activated chloride channel, has emerged as a strong candidate to drive 11q13 amplification in HNSCC by providing growth advantage to tumours and favouring metastatic dissemination." (PMID 26498851, 2015). "Our study showed that silencing ANO1 might be useful to prevent tumor metastasis at least in OSCC." (PMID 24316695, 2014). "Using the Oncomine database to determine the expression of ANO1 in normal and malignant tissues from a variety of tumor types, the Duvvuri group found that although ANO1 may be expressed at a high level in normal breast tissue, its expression is even higher in neoplastic breast tissue." (PMID 24639373, 2014).
tumor (continued). "Thus, analysis of the ANO1 expression pattern in tumours could be used for the prediction or treatment of cancer." (PMID 22102040, 2011). "ANO1 was selected for further study because it is a membrane protein that is exposed at the surface of the cell, which might potentially be used for the development of antibody-based tumour therapies." (PMID 20664600, 2010). "In cancer, ANO1 regulates key signaling pathways, including EGFR, MAPK/ERK, and PI3K/Akt, driving tumor growth and metastasis." (PMID 40356890, 2025). "Knockdown of ANO1 in HNSCC reduces MCL1 expression, redistributes p27Kip1 to the nucleus and perinuclear region, induces cell cycle arrest, inhibits tumor proliferation, and promotes apoptosis." (PMID 40356890, 2025). "GIHCG knockdown suppresses tumour growth by reducing the direct binding of GIHCG to miR-29b-3p and inhibiting ANO1 production." (PMID 40396170, 2025). "According to ingenuity pathway analysis, ANO1 modulates the antiangiogenic factor insulin-like growth factor-binding protein 5 (IGFBP5), which in turn regulates IGF/IGFR signalling in the tumour microenvironment and hence promotes tumour growth." (PMID 40396170, 2025). "Studies have shown that abnormally high expression levels of TMEM16A (also called ANO1), a calcium-activated chloride channel (CaCC), contribute to the occurrence and proliferation of many kinds of tumor cells." (PMID 39070550, 2024). "Upon the failure of immunotherapy, the ANO1 gene is upregulated, activating the PI3K-Akt pathway, resulting in the expression of NRF2/SLC7A11 proteins and inhibiting oxidative stress in tumor cells." (PMID 38853203, 2024). "We further discussed the impact of ANO1‐recruited CAFs on CD8+ T cells, the major performer of anti‐tumor immunity." (PMID 37341301, 2023). "The findings revealed that ANO1, AQP9, and BEST2 were upregulated in tumor tissues, and AQP5, SCN4A, and SCNN1G expression was upregulated in normal tissue from 12 HNSCC patients." (PMID 36389709, 2022). "The training group was divided into four subgroups (ANO1−/MMP3−, ANO1+/MMP3−, ANO1−/MMP3+, and ANO1+/MMP3+) based on the expression status of ANO1 and MMP3 in ESCC tumor tissues." (PMID 31793228, 2020). "Three genes were selected, namely, ANO1, GAL, and MMP3, which were aberrantly expressed in ESCC tumor tissues (P < .001)." (PMID 31793228, 2020). "The positive expression rates of ANO1, GAL, and MMP3 in ESCC tumor tissues were significantly higher compared to those in normal tissues (all P at <.001)." (PMID 31793228, 2020). "Immunohistochemical expression of ANO1, β-catenin, MMP9, snail, and E-cadherin were observed in the cytoplasmic membrane, cytoplasm, and nuclei of tumor cells and the expression of cyclin D1 was observed in the nuclei of tumor cells." (PMID 29416639, 2018). "Cancer-related genes including ANO1, CCND1, CTTN, FADD and ORAOV1 are involved in tumour cell proliferation, evasion of apoptosis, invasion, and migration." (PMID 28384287, 2017). "Differences in DNA methylation at the ANO1 promoter in HPV− and HPV+ TCGA samples were validated with additional tumor samples using EpiTYPER, a quantitative DNA methylation tool utilizing MALDI-TOF mass spectrometry." (PMID 29123240, 2017). "Cells from peripheral blood mononuclear cells tested positive for anoctamin 1, calcium activated chloride channel, ANO1 (DOG1) were considered as tumor CTC of GISTs." (PMID 27153560, 2016). "To test this, we serum starved KP and KPH2 tumour-derived cells for 24 h, and then treated with replete media plus dimethyl sulphoxide (DMSO) or CaCCinh-A01, a small molecule inhibitor of ANO1 activity." (PMID 26837714, 2016). "ANO1 gene amplification was frequently detected in both premalignant lesions (63%) and HNSCC tumours (58%), whereas concomitant ANO1 expression occurred at a much lower frequency (20 and 22%)." (PMID 26498851, 2015).